C3 (complement C3)
Diseases named in the same sentence as C3 in open-access papers (continued):
Sharing a sentence is not in itself a finding about the gene and the disease.
bacterial infections (continued). "CI-induced C3 enhancements at early time points could be expected to protect against early bacterial infection caused by RI or CI." (PMID 28934227, 2017). "Persons who have a C3 deficiency are susceptible to bacterial infection." (PMID 24175013, 2013). "Those novel functions of C3 prompted us to further investigate its roles in inflammation and bacterial infection that go beyond canonical opsonization." (PMID 41441980, 2025). "Autoantibodies to the C4 component of the classical pathway's C3 convertase (C4b2b), the C4 nephritic factor (C4NeF), causes stabilization of C3 and C5 convertases and consumption of C3, leading to recurrent bacterial infections secondary to the low C3." (PMID 38406130, 2024). "We observed that C3 was localized to S. aureus following bacterial infection, most S. aureus were C3 positive or with partial C3 deposition at 2, 4, and 6 hpi." (PMID 39310788, 2024). "Previously, complement C3 was shown to be essential for platelet-mediated CD8+ T cell activation during bacterial infection." (PMID 38054006, 2023). "We also report that fructose mainly enhances the expression of lysozyme and C3, which enable the bacteria to be reduced more efficiently, thus highlighting a metabolism-based approach to combat bacterial infection in aquaculture." (PMID 35386717, 2022). "Activation of the complement pathway results in the production of bioactive C3a, a product of C3 cleavage, which interacts with membrane-bound receptor C3aR to regulate innate immune cell function and outcome of bacterial infection." (PMID 35925892, 2022). "The study indicates that the C3 gene plays a role in resistance to bacterial infection and can be used as a molecular marker for complement activity and traits related to milk production." (PMID 35771868, 2022). "Results from this study imply that the C3 gene plays a role in resistance to bacterial infection and that it can be used as a molecular marker for complement activity and traits related to milk production." (PMID 35771868, 2022). "The exogenous administration of complement component C3 and the active form C3a in Japanese flounder increased its survival against bacterial infection by inducing chemotaxis to peripheral blood leukocytes." (PMID 36389821, 2022). "Among targeted APPs, the decrease in the amount of C3 protein in the secretome of Listeria-infected hepatocytes, compared to non-infected hepatocytes, is particularly striking, given the critical role of C3 in the response to this bacterial infection." (PMID 34858876, 2021). "Pathological changes such as exuviation, inflammatory cell infiltration and reduced levels of IgG and complement C3 occur in the radiation-induced rats, which results in bacterial infection." (PMID 24137307, 2013). "CFI deficiency is possibly an underestimated defect and the eventual existence of this deficiency should be tested in those patients exhibiting low C3 and recurrent bacterial infections." (PMID 22710145, 2012). "In cells deficient of C3 almost no translocation was observed, in stark contrast to WT cells where significantly more p65 was found in the nucleus after treatment and bacterial infection." (PMID 41441980, 2025). "In addition, airway epithelial C3 — distinct from systemic C3 — protects against lung injury in response to bacterial infection." (PMID 40309766, 2025). "Consequently, we sought to further investigate the role of intracellular C3 in bacterial infection and inflammation in epithelial cells." (PMID 41441980, 2025). "The basic attention is devoted to the immune-modulating activity of TDNG following exposure to the bacterial infection (P. putida) which is indicated by augmenting levels of C3 and LYZ plus up-regulation of the response of the BCL-2 and down-regulation of caspase-3." (PMID 38561720, 2024). "Based on these results, we speculated that C3 interaction with bacteria played an important role in the elimination of bacterial infection." (PMID 35281048, 2022).
bacterial infections (continued). "Interestingly, taurine and malate alleviated the expression of Cox-2, IL-1β, IL-6, IL-8, and elevated the expression of C3 after bacterial infection." (PMID 32316833, 2020). "Strikingly, deficiency or a defect in factor H and factor I are known to increase the susceptibility to bacterial infections, due to lack of C3 regulation." (PMID 23326231, 2013). "By stabilizing the convertase and prolonging its natural degradation, “pathogenic” C3NeF can lead to excessive complement activation and C3 hypocomplementemia in non-infective states, which may increase the risk of bacterial infections." (PMID 41550931, 2025). "He does not exhibit increased susceptibility to pyogenic bacterial infections, as reported in patients with homozygous loss-of-function variants in C3 which cause C3 deficiency, although infections may have been prevented by prophylactic antibiotic treatment." (PMID 34248927, 2021). "Beyond its role on immune cells, C3 could also counteract bacterial infection within hepatocytes." (PMID 34858876, 2021).
neurodegenerative disease (43 papers, 2011 to 2026). A disorder of the central nervous system characterized by gradual and progressive loss of neural tissue and neurologic function. "It has been observed that complement molecules, including C1q and C3, are located at synapses and mediate synapse loss in neurodegenerative diseases through the action of phagocytic microglia 12,34,35." (PMID 40860146, 2025). "Expression of complement component 3 (C3) was identified as a hallmark of A1-like astrocytes and has also been detected in the aging brain and in several neurodegenerative diseases, such as AD, PD, and HD." (PMID 41155586, 2025). "A1 astrocytes are induced by pro-inflammatory microglia, express specific markers such as C3 and are associated with various pathological conditions including neurodegenerative diseases and aging." (PMID 34604212, 2021). "Elevated C3 has been implicated in the accumulation of neurotoxic proteins within neurons and synapse loss in mouse model and human AD brains, and C3-positive reactive astrocytes are detected in most neuroinflammatory and neurodegenerative diseases." (PMID 37507386, 2023). "As the central component of the complement cascade, C3 is dysregulated in multiple neurological diseases, particularly neurodegenerative diseases." (PMID 41321642, 2025). "Complement component 3 (C3) is involved in all pathways of complement activation and has been extensively studied in the context of CNS neurodegenerative diseases." (PMID 38840777, 2024). "The exact function of astrocytic C3 is context-dependent, but it has been shown that reactive astrocytes upregulate C3 in neuroinflammatory and neurodegenerative diseases, demonstrating C3 as a marker of astrogliosis." (PMID 39739680, 2024). "Complement component 3 (C3) is also induced in neurodegenerative diseases and is upregulated by proinflammatory cytokines such as IL-1β, gamma interferon (IFN-γ), and tumor necrosis factor alpha (TNF-α) (25, –, 28)." (PMID 37191498, 2023). "Complement component 3 (C3) is known to be upregulated in the course of neurodegenerative diseases, but is also expressed by microglial cells." (PMID 34572572, 2021). "In fact, although A1 astrocytes are neurotoxic in vitro, the in vivo evidence for the A1 state in disease is confined to the presence of elevated C3 expression in post mortem samples from a variety of neurodegenerative diseases." (PMID 31924446, 2020). "The finding of increased CSF C3 levels supports the notion of a dysregulation of the complement system in MS and is in line with previous findings in neurodegenerative diseases." (PMID 25835709, 2015). "Complement component 3 (C3) is one of the most prominent molecular markers delineating neurotoxic reactive astrocytes from alternatively activated astrocytes, and is reportedly elevated in neurodegenerative disease." (PMID 38317225, 2024). "In summary, complement C3 is a reliable marker of brain injury and neurodegenerative diseases." (PMID 38035266, 2023). "CSF levels of the central complement component C3 have been shown to correlate with degree of neurological impairment in several neurodegenerative diseases, but any relation to disease severity in MS is unknown." (PMID 25835709, 2015). "While C3 has been shown to be synthesized by astrocytes and microglia in culture and in brain tissue by in situ hybridization in neurodegenerative diseases or with injury or inflammation, reports of the association of both native and activated C3 differ among mouse models of neurodegeneration." (PMID 21235806, 2011). "Among the immune-related protein interactors of Kv1.3 that were measured by our MS studies, we nominated C3 and STAT1 as proteins of interest to be validated by Luminex based on their known role in several neuroinflammatory and neurodegenerative diseases." (PMID 38936775, 2024).
neurodegenerative disease (continued). "S100β, in combination with the complement protein C3, is a marker for reactive astrocytes in prion and other neurodegenerative diseases, as is lipocalin 2 (LCN2) in combination with C3." (PMID 38786054, 2024). "The interaction between C3 and the Mac1-NOX axis not only unveils the regulation of C3 in chronic neuroinflammation but provides a potential therapeutic target for developing new interventions for neurodegenerative diseases by inhibiting the C3 production and A1 neurotoxic astroglia formation." (PMID 37268807, 2023).
cardiovascular diseases (25 papers, 2010 to 2026). "Complement C3 is considered as a signal of the inflammatory process and future risk of developing cardiovascular diseases." (PMID 22808203, 2012). "C3 has been identified as the central component of the complement system and plays an important role in the pathogenesis of cardiovascular diseases." (PMID 31829184, 2019). "C3 content is increased significantly in some cardiovascular diseases, and cleavage of C3 is the main step in the complement activation cascade." (PMID 29466390, 2018). "A BET inhibitor was recently reported to downregulate basal and cytokine-simulated expression of complement components in cultured hepatocytes and humanized mice, and to reduce activated complement C3 and C5 levels in the circulation of cardiovascular disease patients." (PMID 39294122, 2024). "Besides, a body of large studies targeting normal population also revealed plasma C3, C4 and MBL level were risk factors for cardiovascular diseases." (PMID 35768780, 2022). "This suggests that C3a and C3 have distinct roles in pathways leading to cardiovascular diseases." (PMID 25646095, 2014).
immune diseases (20 papers, 2008 to 2026). "The data presented show that three of seven proteins (ceruloplasmin, Complement C3 and Complement C6) are functionally implicated in immune disease and inflammatory response, DNA replication and cellular assembly and organization." (PMID 32620920, 2020). "Complement C3 and C4 play key roles in the main physiological activities of complement system, and their deficiencies or over-expression are associated with many clinical infectious or immunity diseases." (PMID 23028341, 2012). "Animal experiments showed that JZD effectively ameliorated renal damage and immune disorders, reduced glomerular scores and vascular wall scores, as well as attenuated IgG and C3 deposition in the kidneys of MRL/lpr mice." (PMID 41466499, 2026). "Worse nutrition status marked by a lower BMI will potentially lead to immune dysfunction including a decreased serum level of C3." (PMID 27611091, 2016). "The immune dysfunction score of C4 pattern also increased signally, while C3 was the lowest." (PMID 35265613, 2022). "In addition to its role in AP, C3 is involved in other diseases, especially in immune diseases." (PMID 36249739, 2022). "Immune system disorders in SLE are characterized by increased dsDNA and IgG levels and decreased C3 levels." (PMID 40918088, 2025). "Patients with HIV, or otherwise immunocompromised conditions, showed obvious immune dysfunction based on the impairment of CD4, CD8, and complement levels of C3 and C4." (PMID 35492344, 2022). "In recent years, studies have confirmed that IgAN is a complex immune disease that involves deposits of the circulating immune complexes (CIC) IgA, C3, and IgG in the mesangial region of the glomeruli." (PMID 31039758, 2019). "DEGs that enriched to “immune system diseases” played critical roles in cell-matrix communication (THY1, LVRN, LUM, TIMP3, SPOCK1, LGALS3BP, FAT2, and SERPINE2) as well as inflammation (IL1R2, CD22, PTGES, TNFSF10, IL2RB, C3, SERPING1, and IL-17RE)." (PMID 30131724, 2018). "Both Serum C3 and C4 levels are heritable traits even in individuals without immune diseases such as SLE." (PMID 23028341, 2012). "Given that there are significant immune disorders including elevated IgA and IgE levels in patients with HSP, we conducted Spearman correlation analysis to determine the potential correlation between the gut microbiota and HSP-related indexes including IgA, IgE, IgG, IgM, C3, D-dimer, and IgA/C3." (PMID 34277463, 2021).
neurological diseases (19 papers, 2017 to 2025). "Complement C3 is highly expressed in reactive astrocytes, where it is associated with the neurotoxic subtype implicated in AD and other neurological disorders." (PMID 40294039, 2025). "We and others have shown that C3 deficiency protects against synapse loss in mouse models for neurological diseases and aging." (PMID 40678242, 2025). "The reactive astrogliosis may secrete various cytokines/chemokines and transform into A1 neurotoxic astrocytes to influence the local inflammatory microenvironment, which is supported by the evidence that astrocytic complement C3 is linked to various neurological diseases." (PMID 37965213, 2023). "Specifically, 2-DG reduced the expression of the inflammatory genes C3, TNFα, LCN2, and IL6, all of which are implicated in various neurodegenerative and neurological diseases." (PMID 35326266, 2022). "Expression alterations of APOA4, HP, and C3 proteins in OCD profile were also mentioned in other neurological diseases." (PMID 29158881, 2017). "Deletion of C1q, C3, or CR3 (CD11b/CD18) reduces microglial engulfment of synapses and protects against memory deficits in aged mice and in models of AD and other neurological disorders." (PMID 35820938, 2022). "The network “Cellular assembly and organization, Neurological disease, Organismal development” was predicted with a high score for EAE-16d in IPA and involved the acute phase proteins HEMO (hemopexin, gene: HPX), A1AT (alpha-1-antitrypsin 1–1, gene: SERPINA1) and CO3 (complement 3, gene: C3)." (PMID 33785790, 2021).
metabolic disorders (15 papers, 2010 to 2026). "Also, the complement system, particularly C3 and the C3/C4 ratio, has been associated with CV disease and metabolic disorders." (PMID 40276257, 2025). "Here we show that MAT-derived complement factor D (CFD) and component 3 (C3) derived from steatotic liver coordinately drive excessive alternative complement activation, resulting in cartilage damage in mice during aging and metabolic disorders." (PMID 42056078, 2026). "Our findings are in agreement with several studies which reported that complement C3 as possible biomarker of cardio-metabolic diseases, and insulin resistance." (PMID 34815491, 2021). "An increase in body fat (despite of having a normal weight) can be accompanied by the changes in thyroid function and inflammatory markers such as complement C3 (early marker of metabolic disorders)." (PMID 31666810, 2019). "Complement component 3 (C3) turns out to be an important protein in metabolic disorders, via either inflammation or the C3 subproduct acylation stimulating protein (ASP) which directly stimulates lipid storage." (PMID 30104553, 2018). "Specifically, C3, Cd74, and Agt expression level was increased (migration of cells function) and they affect the endocrine system disorders, gastrointestinal disease, and metabolic disease functions." (PMID 23874995, 2013). "Epidemiological data proposed that circulating complements and their cleavage product concentrations (such as C3, C3a, and C5a) were increased in NAFLD and other metabolic disorders." (PMID 37180779, 2023).
inflammation (12 papers, 2012 to 2025). Aberrant reaction of the microcirculation characterized by movement of fluid and leukocytes from the blood into extravascular tissues. "In conclusion, the present study showed that C3-deficient mice exhibited more severe lung inflammation and increased pulmonary cell apoptosis in a mouse model for SSc." (PMID 39737181, 2024). "Complete FI deficiency has been associated with a consumptive C3 deficiency and recurrent infections with encapsulated microorganisms or aseptic cerebral inflammation while heterozygous mutations in CFI have been liked to immunopathology in the form of atypical haemolytic uraemic syndrome and AMD." (PMID 39584280, 2025). "Several of these proteins were significantly associated with biomarkers of immune complex deposition, elevated SLE-specific antibodies and decreased C3, further implicating them as a signature of active renal inflammation." (PMID 31594956, 2019). "Our results revealed an unexpected anti-inflammatory role of C3 in pulmonary inflammation." (PMID 39737181, 2024). "Levels of complement C3 and C4 are also increased in chronic inflammation." (PMID 28562335, 2017).
kidney (10 papers, 2013 to 2025). "The deposition of MBL, C3, C6 and C9 in the kidney following IR and the deficiency of Crry (a C3 inhibitor) increased the susceptibility of mice to kidney IR injury, corroborating the notion that complement activation during IR contributes to the inflammatory response." (PMID 23295066, 2013). "Evidence suggests that following the induction of acute kidney injury in C3 knockout mice, the impairment of renal function is less pronounced compared to wild-type mice." (PMID 40242472, 2025). "Moreover, C3 KO mice (C3 KO) with IRI exhibited attenuated kidney damage and decreased neutrophils and NETs." (PMID 35250972, 2022). "Meanwhile, ICI-induced kidney injury primarily presented as ATIN, frequently accompanied by glomerular IgA deposition and reduced serum complement C3, highlighting the involvement of humoral immune perturbations." (PMID 41290561, 2025).
hematologic disorder (9 papers, 2010 to 2025). A disease involving the hematopoietic system. "High C3 levels indicate inflammation, which may be associated with many hematological malignancies." (PMID 38023151, 2023). "The mean serum C3 level was lower in patients with hematological malignancies than in those with MGRS or MGUS." (PMID 38561447, 2024). "In hematologic malignancies, renal injury associated with MCL usually also contains renal deposition of C3 or polyclonal immune deposits." (PMID 39009965, 2024). "In a study of patients with SLE comparing low C4 levels alone with low levels of both C3 and C4, the frequency of serositis and hematologic disorders was lower, and the severity of renal and hematologic disorders was milder in the cases with low C4 levels alone." (PMID 36830735, 2023).
infectious disease (9 papers, 2007 to 2026). A disorder directly resulting from the presence and activity of a microbial, viral, or parasitic agent in humans. "Infectious diseases cause an increase in complement components (C3, C4, C9, Factor B, C1 inhibitor, C4b-binding protein, Mannose-binding lectin)." (PMID 34349754, 2021). "Dogs with a genetically determined deficiency of complement C3 more often develop renal and infectious diseases." (PMID 17626630, 2007). "Low complement C3, normal ADAMTS13, and negative rheumatology and infectious disease panels suggested aHUS." (PMID 34912617, 2021).